ZBP1 (Z-DNA binding protein 1)
Diseases named in the same sentence as ZBP1 in open-access papers (continued):
Sharing a sentence is not in itself a finding about the gene and the disease.
infection (continued). "Infection with an engineered MCMV variant with a mutational disruption of the viral M45 RHIM domain core tetrad led to ZBP1- and RIPK3-dependent but RIPK1-independent necroptosis, which emphasizes the enormous contribution of this protein to immune evasion and latent infection." (PMID 36040212, 2022). "Among various pathogenic infections, high fever is also a common symptom, in which heat stress may eliminate pathogens by activating ZBP1 to promote cell death." (PMID 36615244, 2022). "In contrast, both MAVS and DAI/Zbp1-deficiency increased the IFN-I response upon MVA-infection." (PMID 34711816, 2021). "Hence, it is noteworthy that viral RNA sensing appears to be the key mechanism by which ZBP1 becomes activated in response to infection by mutant MCMV expressing a RHIM-mutated M45/vIRA." (PMID 30050058, 2019). "In this review, we systematically elucidated the elaborate ZBP1 signaling mechanism and the antagonistic strategies of host or pathogen, which will lay the foundation for developing highly efficient therapeutics for pathogenic infections, auto-inflammatory diseases, and cancer." (PMID 36142136, 2022). "This work highlights the functional variability of Zα domains and narrows down the potential physiological substrates of ZBP1 in infection and disease." (PMID 42079158, 2026). "A study showed that ZBP1 also contributed to Unfolded Protein Response (UPR) activation during infection." (PMID 41471852, 2025). "Twelve hours post-infection, Zbp1-/- mice exhibited significantly reduced neutrophil death in the BALF, along with increased BALF neutrophil counts and mild increases in total cell numbers." (PMID 40359428, 2025). "First, it was necessary to determine the cell types with high Zbp1 expression in response to AC infection." (PMID 39853924, 2025). "We showed that ZBP1 plays a role in viral clearance and in virus-induced cell death in the lungs following infection with MA10." (PMID 40416961, 2025). "Zbp1 upregulation was observed 4 h post‐infection, with BMDMs exhibiting higher sensitivity to IFN‐γcompared to microglia." (PMID 39853924, 2025). "Combination therapies and smart materials, such as sequential interventions (enhancing ZBP1 early during infection and inhibiting RIPK1 later) or microenvironment-responsive materials (such as pH-triggered drug-release hydrogels) are promising." (PMID 41583472, 2025). "The results revealed that the proportion of DCs increased from 0 to 0.45% (p < 0.0001) after AC infection and decreased to 0.35% (p < 0.001) in Zbp1‐knockout brains." (PMID 39853924, 2025). "Early infection induces ZBP1-dependent PANoptosis for rapid pathogen clearance (within 6 h of IAV infection); however, prolonged inflammation triggers IFN–γ–IRF1–ZBP1 feedback, leading to tissue damage, as observed in cases of septic lung failure." (PMID 41583472, 2025). "While the function of ZBP1 during infection and inflammation has been well reported, its physiological role during environmental stress remains largely elusive." (PMID 41135682, 2025). "To further examine the expression of Zbp1 in microglia/macrophages after AC infection, we performed in vitro experiments using BMDMs and the microglial cell line N9." (PMID 39853924, 2025). "Our findings are consistent with the well-established role of ZBP1 in impeding viral replication as a potent activator of innate immunity during infections." (PMID 40416961, 2025). "To further investigate the dynamic changes in Zbp1 levels after AC infection, we also performed RT‒qPCR and western blot experiments on the brain tissues of mice 0, 7, 14, and 21 days after infection with AC." (PMID 39853924, 2025). "During infection, ZBP1 responds to IAV and forms the ZBP1-RIPK3 complex, which then facilitates recruitment of RIPK1 and further forms ZBP1-PANoptosomes with ZBP1/RIPK3/RIPK1/FADD/CASP8 as the main components." (PMID 40568592, 2025).
infection (continued). "FISH and IF staining demonstrated that, after infection with P. gingivalis, the bacteria were engulfed by BMDMs, accompanied by increased Zbp1 expression in the infected macrophages." (PMID 40307566, 2025). "The proportion of NK cells was upregulated to 1.4% after AC infection (p < 0.0001) but decreased to 0.45% in Zbp1‐knockout mice (p < 0.0001)." (PMID 39853924, 2025). "The expression level of ZBP1 further increased at day 3 post infection (mean fold change = 16.9) followed by a decrease at day 6 post infection (mean fold change = 4.4)." (PMID 40416961, 2025). "IRF1 also regulates the expression of key components necessary for NLRP3 and AIM2 activation after infection, including ZBP1 and guanylate-binding proteins." (PMID 40018047, 2025). "Overall, we found that BST2, ZBP1, CXCL11, and IFITM1 are associated with infection with SARS-CoV-1, SARS-CoV-2 WA-1 and Omicron BA.1, hepatitis C virus, HIV, and influenza virus." (PMID 39874350, 2025). "Our research provides important new insights into ZBP1's role in environmental stress-induced cell death, expanding our understanding beyond its established functions in infection and development." (PMID 41135682, 2025). "During the early stage of infection, ZBP1 activates the NF-κB and MAPK signaling pathways, thereby enhancing phagocytic capacity." (PMID 41471852, 2025). "Immunohistochemistry confirmed that the number of Zbp1‐positive cells significantly increased after AC infection." (PMID 39853924, 2025). "Kanneganti’group first discovered in 2016 that the influenza A virus (IAV) can be recognized by Z-DNA binding protein 1 (ZBP1) after infection." (PMID 40364845, 2025). "ZBP1, a Z-form nucleic acid sensor, plays crucial roles in infection and inflammation by mediating cell death through interactions with other RHIM-containing molecules." (PMID 41135682, 2025). "For example, ZBP1-mediated recognition of Z-RNA can induce necroptosis during infection of influenza A virus (IAV) to drive disease severity." (PMID 41488643, 2025). "We previously reported that West Nile virus (WNV) infection induced a significant increase in ZBP1 expression in mouse brains and in infected primary mouse cells." (PMID 40416961, 2025). "Research indicates that reducing ZBP1 expression in the lungs of mice can attenuate pulmonary inflammatory responses during infection." (PMID 38402193, 2024). "Here, we show that RIPK1 is crucial for ZBP1-driven cell death triggered in human cells during HSV-1(ICP6mut) infection, where it facilitates the assembly of a stable ZBP1-RIPK3 amyloid complex." (PMID 39345610, 2024). "Accordingly, infection or cellular stressors can lead to cell death by the combinatory crosstalk of pyroptotic, apoptotic, and necroptotic molecules (like ZBP1, RIPK1, RIPK3, CASP1, CASP8, and NLRP3, MLKL, and GSMDs) to effectively control pathogenic invasion." (PMID 38590437, 2024). "Among the Zbp1+/+ mice, 4/8 and 3/8 survived after infection with ΔVP22 and ΔVP22 (51–246 aa), respectively." (PMID 39475237, 2024). "3D4/21 cells were infected by SVA (MOI of 1), western blot showed that SVA infection promoting the expression of ZBP1 from 12 to 36 h.p.i." (PMID 38822277, 2024). "Although, ZBP1-dependent cell death has been reported in infections with Francisella novicida and Mycobacterium tuberculosis (Mtb)." (PMID 39850894, 2024). "RIPK1 degradation with R1-ICR-3 treatment prevented RIPK3, especially activated RIPK3 (pRIPK3), from binding to ZBP1 during HSV-1(ICP6mut) infections." (PMID 39345610, 2024). "In Zbp1+/+ BMDMs, the IL-1β level was significantly higher upon infection with ΔVP22 or ΔVP22 (51–246 aa) than with viruses containing an intact N-terminal 1–50 aa VP22 domain." (PMID 39475237, 2024). "During evolution, viruses have evolved various strategies to block ZBP1 signaling and ensure efficient infection." (PMID 39475237, 2024).
infection (continued). "When triggered by pathogen infection, ZBP1 potentially initiates PANoptosis which involves the activation of cell death pathways such as pyroptosis, apoptosis, and necroptosis." (PMID 39850894, 2024). "During IAV-infection ZBP1 can also engage pyroptosis by caspase-1 activation and gasdermin D (GSDMD) pore formation." (PMID 38778049, 2024). "Emerging evidence demonstrates that ZBP1 plays an important role during infections with different viruses." (PMID 39475237, 2024). "Later during infection, at 12 dpi, the top ten significantly upregulated genes with highest fold change included, similar to 4 dpi, Zbp1, Oas2, Gbp1, Ddx60, Oas1a and Mx1." (PMID 38536871, 2024). "3D4/21 cells were infected with SVA at different dose (MOIs of 0.5, 1, 2, and 3) for 24 h and the expression of ZBP1 was induced by SVA infection (P < 0.01)." (PMID 38822277, 2024). "This is in line with results of our previous work, where we observed an upregulation of both Mlkl and Zbp1 upon infection with our mouse adapted strain (P21) in a bulk RNAseq analysis of lungs." (PMID 38286985, 2024). "Altogether, these findings support the idea that HSV-1(ICP6mut) infection triggers ZBP1-driven necroptosis in human cells." (PMID 39345610, 2024). "During infection with the vaccinia virus, ZBP1 is activated by Z-form RNA, dependent on the concerted function of two distinct dsRNA binding domains." (PMID 39772130, 2024). "It was observed that the increase in BiP protein level occurred at 16 hours post-infection, and this enhancement relies in the presence of ZBP1." (PMID 39850894, 2024). "As a potent innate immune sensor, ZBP1 plays an essential role against multiple pathogen infections, particularly viruses." (PMID 39475237, 2024). "To further identify the function of human ZBP1 under pathogens infection, we transfected full-length ZBP1 and Zαβ into HeLa cells, respectively." (PMID 38982083, 2024). "Z-DNA binding protein 1 (ZBP1) is another innate immune sensor that recognizes Z-RNA generated during IAV-infection leading to RHIM-mediated recruitment and activation of receptor interacting kinase 3 (RIPK3) followed by apoptosis and necroptosis." (PMID 38778049, 2024). "In Zbp1+/+ BMDMs, the expression of inflammatory factors was significantly increased upon infection with ΔVP22 compared with infection with PRV-WT." (PMID 39475237, 2024). "The results demonstrated that only the transcription levels of Zbp1 and Nlrp6 were upregulated in all five cell lines upon oHSV infection." (PMID 38693119, 2024). "Herpes simplex virus 1 also induces ZBP1-mediated apoptosis, necroptosis and pyroptosis of cells during infection." (PMID 39614405, 2024). "The prudent use of ZBP1, which is a double-edged sword, has significant clinical implications for treating infections and inflammation." (PMID 38402193, 2024). "As anticipated, the interaction between RIPK3 and ZBP1 was stronger following ΔVP22 or ΔVP22 (51–246 aa) infections than following infection with viruses with intact VP22 1–50 aa domain." (PMID 39475237, 2024). "ADAR1 seems to have a prolonged impact primarily in mild or persistent infections, whereas ZBP1 swiftly triggers an immune response by promptly initiating cellular necrosis in more severe infections." (PMID 37771585, 2023). "The conclusion is that MYCN mediated anti-inflammatory response, CDKN2A mediated ion-channel transport and ZBP1 mediated leishmania-infection." (PMID 37878133, 2023). "A contribution of ZBP1 to immunopathology is also seen during infection with SARS-CoV-2 or mouse hepatitis virus (MHV), two members of the positive-stranded ssRNA Coronaviridae." (PMID 37450010, 2023). "Together, these data suggest that IRF1 contributes to ZBP1-mediated PANoptosis in response to stimulation with IFNγ plus KPT-330 and infection with IAV by regulating ZBP1 expression." (PMID 37557956, 2023). "ZBP-1 participated in effective host defense pathways that reduce the duration of infection by driving cell death in early infection." (PMID 37631988, 2023).
infection (continued). "It has been shown in mice that ZBP1/DAI is a RHIM adaptor able to recruit RIPK3 to drive virus-induced necroptosis during infection with RHIM suppressor mutant herpesviruses." (PMID 37083451, 2023). "Consistent with our cell death data, we found that the activation of these PANoptosis molecules was completely abrogated at 12 h post-infection in IAV-infected Zbp1−/− BMDMs, and we observed a similar phenotype in Ripk3−/−Casp8−/− BMDMs." (PMID 38005819, 2023). "More recently it has been shown that ZBP1 can be activated by endogenous dsRNA in the context of infection, but also in sterile settings." (PMID 37292201, 2023). "Activation of ZBP1 during infection induces innate immune or inflammatory responses as well as different forms of cell death." (PMID 37292201, 2023). "Pan caspase inhibition prevented significant differences in the final percentage of cell death at 24 h between ZBP1+/+ and ZBP1−/− derived cells following infection with any HSV-1 strain." (PMID 35549723, 2022). "Activation of ZBP1, i.e. upon infection with murine cytomegalovirus (MCMV) or IAV, leads to the recruitment of RIPK3 via RHIM interactions which mediates cell death." (PMID 36240069, 2022). "ZBP1-PANoptosome initiates PANoptosis and plays a double-edged sword role in anti-infection and development." (PMID 36142136, 2022). "In turn, some pathogens have developed diverse tactics to block the ZBP1 signaling to ensure efficient infection." (PMID 36142136, 2022). "We also discussed the pathogens and host-developed multiple regulation strategies for ZBP1-mediated signaling; ZBP1 plays a double-effective role in infection and host health." (PMID 36142136, 2022). "In recent years, much attention has focused on the role of ZBP1 in the fight against infection due to its role as an intracellular sensor of Z-form nucleic acids, and ZBP1 expression is tightly connected with inflammatory, especially IFN, signaling." (PMID 36040212, 2022). "ZBP1 functions as crucial adaptor for RHIM-dependent activation of RIPK3-dependent necroptosis during MCMV infection and has more recently been implicated in the induction of necroptosis by influenza as well as vaccinia virus (VACV)." (PMID 35464953, 2022). "Compared to changes in inflammatory cytokine levels, ZBP1 knockdown only mildly attenuated the infection‐induced expression of IFNB and the interferon‐induced gene IFIT1 (Fig EV5F)." (PMID 36268590, 2022). "During pathogen infection, ZBP1 can be essential for activation of NLRP3, possibly recruiting NLRP3 after polyubiquitination during infection." (PMID 35626718, 2022). "ZBP1 can induce PANoptosis of cells when it senses the Z-RNA produced during infection with influenza virus." (PMID 36184616, 2022). "In the early stage of infection, the upregulated ZBP1 via IFN-I intervention induces the appropriate death of infected cells which results in a mild inflammatory response to help host clear the invaded SARS-CoV-2." (PMID 36142136, 2022). "Understanding the impact of ZBP1 signaling on host or pathogens and developing novel positive or negative regulated drugs against ZBP1 signaling will be helpful to anti-infection, alleviation of inflammatory disease, and anti-tumor immunity." (PMID 36142136, 2022). "The attenuation of the pro‐inflammatory response after infection correlated with the efficacy of the individual shRNA to silence ZBP1 expression; shZBP1‐50 resulted in a substantially stronger attenuation than did shZBP1‐52 or shZBP1‐53." (PMID 36268590, 2022). "As a potent innate immune sensor, ZBP1 plays an essential role in immune defense against multiple pathogens infection, including viruses, bacterium, fungi, and parasites." (PMID 36142136, 2022). "Infection with SARS‐CoV‐2 (MOI = 2) showed that knockdown of ZBP1 attenuated the expression of the measured cytokine genes, as well as the production of CXCL10 and to a lesser degree of IL‐6." (PMID 36268590, 2022).
infection (continued). "ZBP1 expression was increased in a time-dependent manner, with a greater increase at 24 and 48 h than at 6 and 12 h post-infection." (PMID 36539813, 2022). "Consistent with ZBP1 as an interferon‐stimulated gene, SARS‐CoV‐2 infection caused the upregulation of ZBP1 mRNA levels in Calu‐3 cells between 48 and 72 h after infection in a dose‐dependent manner." (PMID 36268590, 2022). "During infection of susceptible cells or mice, M45mutRHIM MCMV triggers ZBP1-mediated necroptosis, cutting short replication and restricting dissemination." (PMID 35464953, 2022). "In this paper, we reviewed the mechanisms of ZBP1 signaling, the effects of ZBP1 signaling on host immunity and pathogen infection, and various antagonistic strategies of host and pathogen against ZBP1." (PMID 36142136, 2022). "Influenza A virus (IVA) infection is sensed by ZBP1, which activates RIPK3 and triggers MLKL-mediated necroptosis and FADD-mediated apoptosis." (PMID 35203445, 2022). "Expression of Zbp1 gene in the UB was increased by 2.8-fold and 2.2-fold at 1 wk and 4 wks post-infection, respectively." (PMID 36490282, 2022). "Recently, ZBP1 has been identified as an important mediator of necroptosis during infection with DNA and RNA viruses." (PMID 35549723, 2022). "Mice deficient in ZBP1 and RIPK3 show increased paralysis upon peripheral ZIKV infection and rapid mortality upon direct infection of the CNS, indicating the possible role of these necroptotic components." (PMID 35587190, 2022). "The percentage cell death at 24 h and the death rates following infection of ZBP1+/+ cells with all strains were all significantly lower in the presence of this inhibitor combination." (PMID 35549723, 2022). "Pathogens need to antagonize ZBP1 signaling to ensure infection, while host needs to regulate ZBP1 signaling to maintain immune homeostasis." (PMID 36142136, 2022). "ZBP1 has been shown to trigger cell death by activating PANoptosis in cells during infection with viruses and fungi." (PMID 35587515, 2022). "The failure of MlklK219R/K219R cells to clear MCMVM45mutRHIM infection phenocopies Ripk3−/−, Zbp1−/− and Zbp1ZBDmut infected cells." (PMID 34099649, 2021). "We also observed that ASC specks colocalized with AIM2, Pyrin and ZBP1 collectively in the same cell at 12 hours post-infection with HSV1 or F. novicida." (PMID 34471287, 2021). "Here we discovered that AIM2 regulated the innate immune sensors Pyrin and ZBP1 to drive inflammatory signaling and inflammatory cell death, PANoptosis, and provide host protection during infections with herpes simplex virus 1 (HSV1) and Francisella novicida." (PMID 34471287, 2021). "Overall, our findings identify a critical interaction between AIM2, Pyrin and ZBP1 that drives innate immune responses during pathogen infection." (PMID 34471287, 2021). "Zbp1/DAI has been reported to trigger cell death during infection with murine cytomegalovirus (MCMV), influenza virus, or VACV." (PMID 34711816, 2021). "Whereas other herpesvirus RHIMs inhibit necroptosis, this new VZV RHIM targets the host RHIM-containing protein ZBP1 to inhibit apoptosis during infection." (PMID 32649716, 2020). "We propose that these complexes containing the RHIM mutant are unable to effectively and stably sequester and inhibit all of the ZBP1 expressed in our system during VZV-RHIMmut infection." (PMID 32649716, 2020). "WT BMDMs had increased secretion of IL-18 following infection with C. albicans or A. fumigatus, whereas the Zbp1–/– and Zbp1ΔZα2/ΔZα2 BMDMs had significantly reduced IL-18 release compared with the WT." (PMID 33109609, 2020). "WNV RNA copies in the brains of ZBP1−/− mice were significantly higher than the WT mice at day 8 after infection with WNV NY99." (PMID 31572318, 2019). "Our data demonstrate that the cell viability of infected ZBP1−/− MEFs was significantly higher than that of the WT MEFs at both 48 and 72 h after infection." (PMID 31572318, 2019).